TNF (tumor necrosis factor)
Diseases named in the same sentence as TNF in open-access papers (continued):
Sharing a sentence is not in itself a finding about the gene and the disease.
Hypoglycemia (continued). "elicit the production of host immunomodulators such as tumor necrosis factor α (TNFα) during infection, which also produces hypoglycemia." (PMID 29216326, 2017). "It was also reported that certain cytokines such as IFN-γ, IL-6, or TNF-α was responsible for the induced hypoglycemia in normal strains of mice." (PMID 24741590, 2014). "Several inflammatory markers including C-reactive protein, interleukin (IL)-6, IL-8, tumor necrosis factor (TNF)-α, and endothelin-1 are increased during hypoglycemia." (PMID 24165454, 2013). "The average time of developing hypoglycemia after initiating TNF-α inhibitor was 4.3 months; the shortest time was one month, and the longest time was six months." (PMID 22234148, 2012). "While all nine patients had at least one bout of a low blood glucose reading, four patients (cases 1, 5, 6, and 7) developed more than one episode of hypoglycemia after initiating TNF-α inhibitor treatment." (PMID 22234148, 2012). "Whereas all of our cases were asymptomatic, pointing to a more biochemical hypoglycemia, all other reported cases with hypoglycemia occurred in diabetic patients who were treated with TNF-α inhibitors and who were symptomatic." (PMID 22234148, 2012). "However, hypoglycemia markedly reduced the expression of interferon-gamma (IFNγ) and, to a lesser degree, tumour necrosis factor-alpha (TNFα), key indicators of effector function, while interleukin-2 (IL-2) production was unaffected." (PMID 40575013, 2025). "Hypoglycemia leads to a physiological response not only of counter-regulatory hormones such as glucagon, cortisol, catecholamines and growth hormone, but also of cytokines such as TNF-α, IL-6, IL-8 and VEGF-A." (PMID 37400734, 2023). "Reports that TNF-α administration can induce hypoglycemia and that it decreases G6Pase expression by activation of NF-κB provide a link between ricin-induced inflammatory response and hypoglycemia." (PMID 36548717, 2022). "The decreased levels of glycine following ricin treatment may exacerbate TNF-α’s deleterious effects observed in this condition, further contributing to hypoglycemia." (PMID 36548712, 2022). "We first described ricin-induced hypoglycemia, and in a concurrent manuscript, we show that hepatic utilization of stored glucose is impaired by suppression of glucose-6-phosphatase expression, most likely mediated by TNF-α." (PMID 36548712, 2022). "However, TNF-α also triggers hypoglycemia; thus, IL-1RA can have only a partial effect in limiting LPS-induced hypoglycemia." (PMID 32513828, 2020). "The PcAS-infected Adx mice still developed lethal hypoglycemia following TNF-α neutralization." (PMID 30375380, 2018). "This suggested that suppression of PPAR-γ expression may be involved in the high levels of TNF-α, IL-1β, and IL-6 induced by hypoglycemia." (PMID 29793504, 2018). "Given TNFα’s role as a proinflammatory cytokine, this hypoglycemia may result either through direct or indirect cytokine actions on host metabolic and immune functions or, more likely, some combination of both." (PMID 29216326, 2017). "This case is an important reminder of the multiple roles of TNF-α in many disease states and the possible side effects, specifically hypoglycemia, which may occur with initiation of anti-TNF-α therapy." (PMID 29721512, 2017). "On the other hand, TNF-α and IL-1β have been demonstrated to induce hypoglycemia." (PMID 28836970, 2017). "Inconsistent with the reported results, we found that injection of a relatively high dose of anti-TNF-α neutralizing antibodies (50 μg/mouse) failed to reverse hypoglycemia caused by anti-CD3 administration." (PMID 24741590, 2014). "It stands to reason, therefore, that the TNF-α inhibitors used to treat RA could indeed induce a state of hypoglycemia with chronic use." (PMID 22234148, 2012). "Whereas many of these are frequently reported in the literature, hypoglycemia, a possible side effect of tumor necrosis factor-alpha inhibitors, may be underpublicized." (PMID 22234148, 2012).
Hypoglycemia (continued). "Furthermore, plasma glucose levels correlated negatively with brain levels of mRNAs encoding TNF-α, IL-1β, IL-6, CCL2 and iNOS, suggesting that hypoglycemia and the expression of these pro-inflammatory markers might be linked." (PMID 30375380, 2018). "The inability of TNF-α neutralization to restore normoglycemia or survival may suggest that TNF-α-mediated inflammation is not the main cause of death and may instead be a consequence of the hypoglycemia." (PMID 30375380, 2018). "These phenomena lead to severe hypoglycemia, liver glycogen depletion, hyperlactatemia and elevated blood FFA levels, all contributing to TNF-induced lethal shock." (PMID 41132685, 2025). "It was reported that anti-CD3 treatment induced hypothermia and hypoglycemia in normal strains of mice, and cytokines such as IFN-γ and TNF-α were shown to be responsible for the hypoglycemia induced by anti-CD3 treatment." (PMID 24741590, 2014). "This was accompanied by more severe hypoglycemia and hyperlactatemia in TNF-treated Slc25a13-/- mice, which was not yet evident in TNF-treated wildtype controls at this 8h post TNF timepoint." (PMID 41132685, 2025). "Many of these were the same metabolites that differentiated the hypoglycemia induced by ricin from that observed following fasting, and suggests that the effects of protein catabolism and TNF-α were not manifest until later in the time course." (PMID 36548712, 2022). "In that study, insulin effect was measured in non-diabetic and diabetic subjects where it was noticed that in non-diabetic subjects, hypoglycemia downregulated the production capacity of TNF-α." (PMID 34067027, 2021). "Along with the drive of the sympathoadrenal activation, several inflammatory markers including C-Reactive Protein (CRP), Interleukin 6 (IL-6), Interleukin 8 (IL-8), Tumor Necrosis Factor α (TNF-α), and endothelin-1, have been shown to be increased during hypoglycemia." (PMID 34572493, 2021). "Together, these data show that the hypoglycemia in infected Adx mice is not reversed by administration of glucose, by blocking insulin release with clonidine or by neutralizing TNF-α." (PMID 30375380, 2018). "To determine whether the effect of AQP4 deletion on BBB disruption after hypoglycemia is involved in the immunomodulatory influence of AQP4 deletion, we examined TNF-α, IL-1β, and IL-6 mRNA expression in the brains of mice." (PMID 29793504, 2018). "This hypoglycemia is not prevented by glucose administration or TNF-α neutralization." (PMID 30375380, 2018). "Our findings indicate that TNF-α is not responsible for anti-CD3-induced hypoglycemia." (PMID 24741590, 2014).
interstitial lung disease (41 papers, 2010 to 2025). A diverse group of lung diseases that affect the lung parenchyma. "Serum level of TNF-α has been identified as the most discriminating factor associated with the presence of interstitial lung disease (ILD) in pSS patients." (PMID 37614232, 2023). "Importantly, however, TNF-alpha inhibitors, in addition to resulting in an increased risk of infection, are also now being seen to cause interstitial lung disease." (PMID 27516887, 2016). "Next, we asked whether other cytokines and growth factors previously implicated in interstitial lung disease, such as TNF-α, IL1β and CTGF, alone or in combination with TGF-β1, would induce or alter the progression of EMT in HBECs." (PMID 20051102, 2010). "Elevated levels of IL-6 and TNFα have indeed been reported in the serum of SSc patients in several studies, and both cytokines are associated with fibrotic processes, disease progression, and the occurrence of interstitial lung disease, especially in dcSSc patients." (PMID 33922041, 2021). "Rituximab-associated interstitial lung disease (ILD) may initially be asymptomatic, and serial monitoring of serum tumor necrosis factor-alpha levels may facilitate timely diagnostic intervention with pulmonary computed tomography." (PMID 41398883, 2025). "In a cohort of 122 RA patients with interstitial lung disease either induced or exacerbated by TNF-targeted therapies, complete resolution was observed in up to 40% after withdrawal of the biologic agent." (PMID 37371850, 2023). "Consistent with previous reports, we found that severe interstitial lung disease appeared in the lungs of TNF-Tg mice." (PMID 35600883, 2022). "TNF-α also contributes to the pathophysiology of interstitial lung disease by inducing the apoptosis of epithelial cells and the sequential release of TGF-β, IL-1β, and IL-1 receptor antagonist (IL-1ra)." (PMID 20137099, 2010). "Following case-mix adjustment, regional variation in the choice of targeted therapy became less marked, indicating the continued influence of these factors on b/tsDMARD choice, despite accumulating evidence supporting the safety of TNF inhibitors in people with cancer or interstitial lung disease." (PMID 39485485, 2025). "Activation of the TNF signalling pathway has been found to induce interstitial lung disease." (PMID 35132912, 2022). "Similarly, subjects with interstitial lung disease were found to have higher levels of IL-6, TNF-α, TGF-β, IFN-γ and other inflammatory cytokines." (PMID 33802067, 2021). "In a different study, it was shown that, in response to combined gefitinib (EGFR inhibitor) and LPS treatment, mice expressing ectopic Fra-1 develop interstitial lung disease, accompanied by diminished levels of TNF-α, MIP-1α and MIP-2 when compared with wild-type mice." (PMID 22911824, 2012). "TOPO-I antigen is overexpressed in interstitial lung disease and overexpressed in FB from patients with SSc and is upregulated by TGF-β and tumor necrosis factor alpha (TNF-α)." (PMID 35837382, 2022). "It appears that anti-TNF-α treatment could be of benefit to a subset of patients with IIM, especially those with early-stage DM with interstitial lung disease." (PMID 29216907, 2017). "Furthermore, thalidomide reduces lipopolysaccharide‐stimulated release of TNF‐α, IL‐8, and IL‐18 (‘necrotic’ cytokines), but not IL‐6, IL‐10, and IL‐12 (p70) (‘inflammatory’ cytokines) from alveolar macrophages in patients with interstitial lung disease." (PMID 38481033, 2024).
postmenopausal osteoporosis (41 papers, 2006 to 2025). Metabolic disorder associated with fractures of the femoral neck, vertebrae, and distal forearm. "In the absence of estrogen, activated T cells secrete IL-17A, RANKL, and TNF, enhancing bone resorption and causing postmenopausal osteoporosis." (PMID 35164658, 2022). "For instance, lncRNA CASC11 is up-regulated in the postmenopausal osteoporosis and is associated with TNF-α." (PMID 34583640, 2021). "Studies have implicated that postmenopausal osteoporosis is partially mediated by the release of pro-inflammatory factors due to estrogen withdrawal, such as IL-6, TNF-α, and IL-1." (PMID 33628184, 2020). "IL-1 and TNFα have long been implicated in osteoclast formation in postmenopausal osteoporosis and in animal models thereof (ovariectomy)." (PMID 24278766, 2013). "Moreover, the presence of signaling pathways related to inflammatory cytokines, such as TNF and IL-17, among the top ranked target-associated pathways highlighted the significant impact of inflammation on bone metabolism in postmenopausal osteoporosis." (PMID 39596387, 2024). "Both falcarindiol and tetrahydrocoptisine demonstrated direct interaction with pro-inflammatory cytokines IL6, IL1B, and TNF, key drivers of osteoclastogenesis and bone resorption in postmenopausal osteoporosis by activating inflammatory pathways linked to bone loss." (PMID 39596387, 2024). "There is growing evidence for the role of kaempferol in attenuating inflammatory response mediated by NF-кB, indicating its protective effects on bone loss in postmenopausal osteoporosis by blocking TNF-α-induced nuclear translocation of the NF-кB subunit p65 from the cytoplasm to the nucleus." (PMID 35154351, 2022). "Interestingly, in estrogen deficiency, activated T cells secrete RANKL, TNF-α, and interleukin (IL)-17A, which amplify bone resorption and contribute to postmenopausal osteoporosis." (PMID 33322156, 2020). "Bone loss in postmenopausal osteoporosis has been addressed by anti-TNFα treatments." (PMID 31031773, 2019). "Previous studies indicated that the chronical postmenopausal osteoporosis may cause an inflammation environment in the patient’s bodies, with the signature of highly expression pattern the pro-inflammatory cytokines, including TNFα." (PMID 36983039, 2023). "LncRNA CASC11 can drive the development of postmenopausal osteoporosis by upregulating tumor necrosis factor-α levels." (PMID 40292220, 2025). "Inflammatory cytokines such as TNF‐α, IL‐1β and IL‐6 are elevated in postmenopausal osteoporosis and have been shown to play a role in the development of the disease." (PMID 38748896, 2024). "TNF-α can lead to impaired bone formation by inhibiting osteoblast differentiation; this plays a central role in the pathogenesis of postmenopausal osteoporosis." (PMID 36673366, 2023). "For example, postmenopausal osteoporosis patients had higher T-cell activity and increased TNFα and RANKL production, which can promote osteoclast differentiation." (PMID 32974344, 2020). "The effects on bone loss observed with anti-IL-17A therapies in animal models of postmenopausal osteoporosis raised the question of a specific effect of this cytokine on the bone compared to other proinflammatory cytokines such as TNF-alpha or IL-6." (PMID 31485194, 2019). "In postmenopausal osteoporosis, bone resorption is also increased by the production of monocyte-related cytokines, such as IL-1, IL-6, and TNF-α, which induce RANKL expression in bone tissue and enhance RANKL-RANK-mediated osteoclastogenesis." (PMID 29348535, 2018). "TNFα has long been recognized as an important cytokine in postmenopausal osteoporosis; however a surprising recent discovery was that T cells are the likely source of this cytokine." (PMID 24278766, 2013). "This work reported that women with postmenopausal osteoporosis exhibit an increased T-cell activity and elevated production of TNFα and RANKL compared to healthy postmenopausal controls inducing OC formation and activity." (PMID 23762093, 2013).
postmenopausal osteoporosis (continued). "Together, these findings indicate that MRPF is a promising functional food ingredient for managing postmenopausal osteoporosis through modulation of the gut–bone axis via the suppression of inflammatory markers, such as TNF-α, and the remodeling of gut microbiota." (PMID 41466098, 2025). "Tetrahydrocoptisine was found to modulate postmenopausal osteoporosis by directly interacting with disease-related proteins such as IL6, IL1B, and TNF, in addition to affecting disease-associated biological functions and indirectly interacting with other disease-related proteins." (PMID 39596387, 2024). "Tumor necrosis factor-alpha (TNF-α) promotes osteoclasts differentiation to enhance bone resorption and inhibits osteoblasts differentiation to impair bone formation, which plays a central role in the development of postmenopausal osteoporosis (PMOP)." (PMID 33425899, 2020). "In vivo blockade of TNF in postmenopausal osteoporosis reduces bone resorption; this suggests that TNF-α increase could be one of the mechanisms responsible for postmenopausal bone loss." (PMID 23935650, 2013). "Additionally, tissue necrosis factors α (TNF-α) was found to promote osteoblast apoptosis and indirectly stimulate osteoclastogenesis via B cell-produced receptor-activator of NF-κB ligand (RANKL), leading to bone loss during postmenopausal osteoporosis." (PMID 38694220, 2024). "Further, the present finding strongly suggests that the antiosteoporotic activity of AKBA may be mediated through its inhibition of the NF-κB-induced TNF-α signaling pathway, which consequently substantiates its possible use in the management of postmenopausal osteoporosis." (PMID 33081068, 2020). "Thus, the increase of sclerostin mediated by TNF-α may at least partially contribute to the pathogenesis of postmenopausal osteoporosis." (PMID 23762093, 2013). "The direct interactions of rutin, beta-sitosterol, quercetin, norisoboldine, and hyperoside with key disease-related proteins such as TGFB1, TNF, IL1B, IL6, and CAT suggested that these compounds may modulate critical pathways involved in the pathology of postmenopausal osteoporosis." (PMID 39596387, 2024).